LRRK2 (leucine rich repeat kinase 2)
Diseases named in the same sentence as LRRK2 in open-access papers (continued):
Sharing a sentence is not in itself a finding about the gene and the disease.
Parkinson disease (continued). "The leucine-rich repeat kinase 2 (LRRK2), a Ser/Thr kinase, is linked to both familial and sporadic Parkinson’s disease (PD)." (PMID 32630525, 2020). "Relevant Parkinson’s Disease (PD)-associated genes PARK7, PINK1, SNCA, and PRKN are expressed at medium-to-high levels, while LRRK2 is expressed at overall lower levels." (PMID 33281596, 2020). "Our results contribute to the understanding of the genetic architecture associated with early onset Parkinson’s disease, showing both PARK2 and LRRK2 play an important role in Spanish Parkinson’s disease patients." (PMID 32870915, 2020). "Recently others have used alternative direct reprogramming methods to generate dopamine like neuronal cells from sporadic and LRRK2 Parkinson’s patient cells." (PMID 32968089, 2020). "Our results demonstrate that this dual inhibitor exerted beneficial effects on the neurodegeneration in LRRK2 parkinsonism." (PMID 33231564, 2020). "Most importantly, for the first time, we show the likely involvement of LRRK2 haploinsufficiency in early-onset cognitive impairment, in stark contrast to late-onset Parkinsonism by the gain-of function mechanism of LRRK2." (PMID 31963867, 2020). "use patient, control, and gene-edited human iPSC macrophages/microglia to examine endogenous expression and function of the Parkinson's disease gene, LRRK2, in this immune subset." (PMID 32359446, 2020). "Overall frequencies of LRRK2, SNCA, and VPS35 mutations according to index case ethnicity, family history of Parkinson's disease and age at onset." (PMID 32849182, 2020). "In the present study, we demonstrated that JMF3086, a dual inhibitor targeting HMGR and HDAC, significantly improved neurite degeneration in LRRK2-G2019S parkinsonism models both in vivo and in vitro." (PMID 33231564, 2020). "LRRK2 is a kinase expressed in striatal spiny projection neurons (SPNs), cells which lose dopaminergic input in Parkinson’s disease (PD)." (PMID 33006315, 2020). "We designed and synthesized a dual inhibitor, statin hydroxamate JMF3086, that simultaneously inhibits HMGR and HDAC, and examined its neuroprotective effects on LRRK2-G2019S parkinsonism." (PMID 33231564, 2020). "This approach remains to be explored more fully, but there is significant interest in targeting the protein kinase LRRK2 for treatment of Parkinson's disease." (PMID 32433026, 2020). "Here, we demonstrated that the dual-acting compound JMF3086 derived from lovastatin and SAHA beneficially rescued neurite degeneration in a LRRK2-G2019S parkinsonism model." (PMID 33231564, 2020). "The leucine-rich repeat kinase 2 (LRRK2) is a large multidomain protein that is associated with familiar and sporadic Parkinson’s disease (PD)." (PMID 32317922, 2020). "Mutations within the Leucine-Rich Repeat Kinase 2 (LRRK2) gene are the most common genetic cause of autosomal and sporadic Parkinson’s disease (PD)." (PMID 32486414, 2020). "Leucine-rich repeat kinase 2 (LRRK2), initially identified as being involved in Parkinson’s disease, influences a wide range of signaling pathways." (PMID 32033485, 2020). "Given the importance of the autophagy pathway in Parkinson’s pathogenesis it is particularly relevant to focus on the role of LRRK2 to discover novel therapeutic approaches that restore lysosomal protein degradation homeostasis." (PMID 32523507, 2020). "Six genes associated with Parkinsonism have been identified, including Parkin, DJ-1, PINK1, α-Synuclein, UCHL-1, and LRRK2." (PMID 31151179, 2019). "Parkinson’s disease is one of the most common neurodegenerative illnesses in older persons and the leucine-rich repeat kinase 2 (LRRK2) is an auspicious target for its pharmacological treatment." (PMID 30763264, 2019). "The leucine‐rich repeat kinase 2 (LRRK2) gene has been extensively studied in relation to both familial and sporadic forms of Parkinson's disease." (PMID 31487119, 2019).
Parkinson disease (continued). "This study suggests that LRRK2, GBA, and PRKN mutations in Parkinson disease are associated with motor improvements after STN DBS, comparable to idiopathic Parkinson disease." (PMID 30707228, 2019). "Mutations in the LRRK2 and GBA genes are the most common known genetic risk factors of Parkinson's disease (PD)." (PMID 31164863, 2019). "Because LRRK2 is a well-known gene involved in the pathogenesis of Parkinson’s disease (PD), most earlier studies were performed in neuronal cells." (PMID 30669622, 2019). "Mutations in LRRK2 and GBA1, which encodes glucocerebrosidase (GCase), are associated with Parkinson’s disease." (PMID 31804465, 2019). "Since the discovery of leucine-rich repeat kinase 2 (LRRK2) as a protein that is likely central to the aetiology of Parkinson’s disease, a considerable amount of work has gone into uncovering its basic cellular function." (PMID 31864390, 2019). "The mean (SD) age at Parkinson disease onset was 43.4 (3.7) years in LRRK2, 44.7 (4.4) years in GBA, and 28.6 (7.7) years in PRKN carriers." (PMID 30707228, 2019). "With specific relevance to Parkinson’s disease, both glucocerebrosidase and leucine-rich repeat kinase 2 seem to be needed for proper functioning of the autophagy/lysosome pathway." (PMID 30654525, 2019). "Parkinson’s disease can be inherited, and mutations in the LRRK2 gene, which codes for the protein leucine-rich repeat kinase 2, have been associated with this neurological pathology." (PMID 31035701, 2019). "In terms of clinical presentation and late age of onset, LRRK2 mediated Parkinson’s closely resembles the common sporadic form of the disease affecting the vast majority of patients." (PMID 31663853, 2019). "It has been shown that LRRK2 alone cannot induce Parkinsonism in a transgenic mouse model but when overexpressed in an α-synuclein transgenic model it does appear to contribute to the acceleration of the disease." (PMID 31969802, 2019). "For example, the pattern of LRRK2 expression significantly related to Parkinson’s disease (PD) differs in distinct neuronal subtypes between rats and mice." (PMID 30887273, 2019). "Using an established model of Parkinson's disease (overexpression of alpha-synuclein), the authors find that an LRRK2 inhibitor rescue Parkinsonism in the cylinder test." (PMID 31685675, 2019). "Mutations in the LRRK2 and GBA genes are the most common inherited causes of Parkinson's disease (PD)." (PMID 31164863, 2019). "Accordingly, a question is raised: “Is LRRK2 detection in human biofluids a potential Parkinson’s disease biomarker?”." (PMID 31551736, 2019). "A strong positive correlation was found between Nrf2 and the Unified Parkinson’s Disease Rating Scale (UPDRS) in LRRK2-PD patients." (PMID 31261912, 2019). "Mutations in seven genes were robustly associated with autosomal dominant (SNCA, LRRK2, EIF4G1, VPS35) or recessive (parkin/PARK2, PINK1, DJ1/PARK7) PD or parkinsonism." (PMID 29881367, 2018). "Leucine-rich repeat kinase 2 (LRRK2) was first discovered in genome-wide linkage studies of patients of Parkinson’s disease." (PMID 29472933, 2018). "The implications of this are highly relevant to the understanding of the physiological role of LRRK2 in the brain and to efforts to target LRRK2 in Parkinson’s disease." (PMID 30223621, 2018). "The present study focused on Rab29 due to the previous genetic links between Rab29, LRRK2, and Parkinson's disease." (PMID 29212815, 2018). "aSYN pathology is a hallmark of PD, has been linked to defects in mitochondrial autophagy, and increased aSYN levels have been observed in DANs from G2019S LRRK2 Parkinson’s disease patients compared to isogenic controls." (PMID 29513666, 2018). "Leucine-rich repeat kinase 2 (LRRK2) is widely expressed in the brain and exerts neurotoxicity in Parkinson’s disease." (PMID 29545743, 2018).
Parkinson disease (continued). "The leucine-rich repeat kinase 2 (LRRK2) gene is one of the main genetic contributors and was first discovered to be associated with Parkinson's in 2004." (PMID 29127255, 2018). "As such there is considerable interest in targeting LRRK2 for the prevention and possibly treatment of Parkinson's." (PMID 29127255, 2018). "Other genes that associate with Parkinson’s disease that were also repressed were NUB1 which encodes a Lewy body protein, and DJ-1 (aka PARK7) whose product can bind LRRK2 and is associated with a recessive form of Parkinson’s disease." (PMID 30374342, 2018). "There is compelling evidence for the role of the leucine-rich repeat kinase 2 (LRRK2) and in particular its kinase function in Parkinson's disease." (PMID 29127255, 2018). "Mutations in leucine-rich repeat kinase 2 (LRRK2), a large multidomain protein kinase of as yet incompletely understood function, represent the most common genetic cause of Parkinson disease and predispose to sporadic Parkinson disease as well." (PMID 30571694, 2018). "It will also be interesting to evaluate the consequences of LRRK2‐mediated Golgi fragmentation in relation to Parkinson's disease." (PMID 29212815, 2018). "For example, in the Parkinson disease-affected brain, EP interacts with leucine-rich repeat kinase 2 (LRRK2) and parkin, serving as a substrate that can be modified by phosphorylation or ubiquitination, which results in synaptic dysfunction and loss." (PMID 30061577, 2018). "It will be important to determine which cells and tissues display the greatest cilia defects in LRRK2 models of Parkinson’s disease, and try to understand how those changes lead to specific loss of dopaminergic neurons in the brain." (PMID 30398148, 2018). "For this reason, the LRRK2 gene is similar to the many critical genes involved in the NOD2-mediated response that is associated with leprosy susceptibility, CD, and Parkinson’s disease (PD)." (PMID 29755459, 2018). "These include the leucine-rich repeat kinase 2 (LRRK2) pathway in Parkinson’s disease (FDR-adjusted P = 9.4e-5) and PD-1/PD-L1 (Programmed Death 1/PD-Ligand 1) signaling pathway (FDR-adjusted P = 6.5e-5)." (PMID 29321020, 2018). "For example, LRRK2 is currently the most promising drug target for Parkinson’s disease, and it is being intensively investigated for that purpose." (PMID 30562929, 2018). "Leucine-rich repeat kinase 2 was first discovered to play a role in Parkinson’s disease, and it has been shown to be involved in various signaling pathways and cellular processes." (PMID 29472933, 2018). "Mutations in leucine-rich repeat kinase 2 gene (LRRK2) are associated with familial and sporadic Parkinson’s disease (PD)." (PMID 29541021, 2018). "There is compelling evidence for the role of LRRK2 and in particular its kinase function in Parkinson's disease." (PMID 29127255, 2018). "Our data also suggest that inhibitors targeting the LRRK2 ankyrin domain would be expected to block Rab29 binding and inhibit activity of LRRK2 in cells, thereby offering therapeutic potential for the treatment of Parkinson's disease." (PMID 29212815, 2018). "We previously reported that Parkinson’s disease (PD) kinase LRRK2 phosphorylates a subset of Rab GTPases on a conserved residue in their switch-II domains (PMID: 26824392)." (PMID 29125462, 2017). "Since the best-described role for LRRK2 is in Parkinson’s disease, we sought to corroborate this idea in mouse brain." (PMID 28103901, 2017). "Leucine-rich repeat kinase 2 induction was also increased in monocytes and dividing T cells in Parkinson’s disease patients compared to healthy controls." (PMID 28649611, 2017). "LRRK2 also helps maintain neuronal integrity against induced Parkinsonism by alleviating the consequences of ER stress." (PMID 28545479, 2017).
Parkinson disease (continued). "In tauopathies, EMVs have been shown to export phosphorylated tau; in Parkinson’s disease (PD), exosomes were shown to export α-synuclein and leucine-rich repeat kinase 2 (LRRK2); and in Alzheimer’s disease (AD), they export amyloid β (Aβ)." (PMID 28587234, 2017). "LRRK2 G2019S parkinsonism is inherited as a Mendelian dominant condition and manifests in heterozygous carriers." (PMID 28930069, 2017). "This is consistent with findings that overexpression of wild-type or mutant LRRK2 induces neural toxicity and elevated protein levels or activity that possibly contribute to Parkinson’s disease." (PMID 28407015, 2017). "High levels of leucine-rich repeat kinase 2 (LRRK2) in immune cells disrupt immune system function in patients with Parkinson’s disease (PD)." (PMID 28649611, 2017). "Ser(P)-1292 LRRK2 levels were found elevated in Parkinson's disease and correlated with features of Parkinson's disease." (PMID 28912682, 2017). "Later, clinical features of LRRK2 G2019S parkinsonism were studied in a 570 unrelated and 288 related patients including 220 sporadic (38%) and 126 familial cases (45%) who were carriers of the mutation." (PMID 28683740, 2017). "Although genes have been identified that can cause Parkinson’s disease, such as SNCA, LRRK2, parkin, PINK1, and DJ-1." (PMID 28989991, 2017). "The aim of this study was to determine the expression pattern of leucine-rich repeat kinase 2 in immune cell subsets and correlate it with the immunophenotype of cells from Parkinson’s disease and healthy subjects." (PMID 28649611, 2017). "We conclude that the GKI mouse is a valuable model in which to probe the etiology and early pathophysiology of LRRK2, and potentially sporadic, parkinsonism." (PMID 28930069, 2017). "In sum, these findings suggest that leucine-rich repeat kinase 2 has a regulatory role in immune cells and Parkinson’s disease." (PMID 28649611, 2017). "Mutations in the leucine-rich repeat kinase 2 gene (LRRK2, PARK8) are the most frequent genetic causes of Parkinson’s disease, reaching up to 40% in some ethnic groups, Ashkenazi Jewish and North African Arab Berbers." (PMID 28582422, 2017). "Recent data suggests a new role for WSB1 as a component of a neuroprotective pathway which results in modification and aggregation of neurotoxic proteins such as LRRK2 in Parkinson’s Disease, via an unusual mode of protein ubiquitinylation." (PMID 27542736, 2016). "Our study firstly expresses that rs1491942 of LRRK2 and rs2301135 of SNCA gene are substantially associated with sporadic Parkinson's disease in Chinese Han population." (PMID 27668119, 2016). "Recently, we discovered that leucine rich repeat kinase 2 (LRRK2), a protein associated with inherited Parkinson’s disease, interacts with specific synaptic proteins and influences synaptic transmission." (PMID 27242426, 2016). "Overall, these findings help elucidate processes of early, pre-degenerative dopaminergic dysfunction in dopamine neurons and synapses in LRRK2-dependent Parkinson's disease." (PMID 26744332, 2016). "Leucine-rich repeat kinase 2 (LRRK2) is a potential therapeutic target for the treatment of Parkinson’s disease (PD)." (PMID 27503089, 2016). "(R1441C) LRRK2 or (G2019S) LRRK2 transgenic mouse at the age of 12-16 months displayed parkinsonism phenotypes of motor dysfunction and cell death of SNpc dopaminergic neurons." (PMID 27509057, 2016). "Other studies also suggest the involvement of CHIP in regulating the levels of other Hsp90 client proteins such as runt-related transcription factor 1 (Runx1) and LRRK2, via UPS, a protein whose mutation is linked to Parkinson’s disease." (PMID 27757073, 2016). "Such mutations generally increase the activity of LRRK2 and so drug companies have developed drugs that inhibit LRRK2 to prevent or delay the progression of Parkinson’s disease." (PMID 26824392, 2016).
Parkinson disease (continued). "The study of protein domains has previously revealed important functional insights, such as the identification of LRRK2 as a promising therapeutic target for the treatment of Parkinson’s disease." (PMID 27128313, 2016). "Parkinson's disease-causing mutations lie in either the GTPase (R1441C/G/H), COR (Y1699C) or kinase (G2019S and I2020T) domains of the LRRK2 protein." (PMID 26744332, 2016). "We aimed to determine if reduced phosphorylation of LRRK2 following inhibitor treatment is also a valid measure of target engagement in peripheral mononuclear cells from Parkinson’s disease patients." (PMID 27503089, 2016). "Both inhibitors showed no acute toxicity in primary cells and both inhibitors reduced the constitutive phosphorylation of LRRK2 at all measured residues equally in both control and Parkinson’s disease groups." (PMID 27503089, 2016). "In the final review, “Activation Mechanism of LRRK2 and Its Cellular Functions in Parkinson's Disease,” the authors discuss the cellular role of LRRK2 and the recent research linking LRRK2-mediated PD to mitochondrial dysfunction and aberrant autophagy." (PMID 27579213, 2016). "Measuring the reduction in LRRK2 phosphorylation resulting from LRRK2 kinase inhibition, is thus a valid measure of acute peripheral target engagement in Parkinson’s disease patients." (PMID 27503089, 2016). "Leucine-rich repeat kinase 2 (LRRK2) is an autosomal dominant, late-onset familial Parkinson's disease (PD) gene." (PMID 26365310, 2015). "Kinetic data for leucine-rich repeat (LRR) kinase 2 (LRRK2) confirms that dimerization is essential for efficient GTP hydrolysis and that Parkinson's disease (PD) mutations cause decreased activity." (PMID 26310572, 2015). "Another group of scientists focused on mitochondrial functions in Parkinson’s disease associated with mutation in the PINK1 and LRRK2 genes." (PMID 25689424, 2015). "Disease models of Parkinson’s disease have been created by generating iPSCs from patients carrying the G2019S mutation in the Leucine-Rich Repeat Kinase-2 (LRRK2) gene, the most common mutation in Parkinson’s disease." (PMID 26633382, 2015). "We would like to thank all the subjects and Parkinson disease patients who donated skin biopsies, and Prof. T. Dawson and Prof. V. Dawson at John Hopkins School of Medicine for the LRRK2 knockout mouse." (PMID 25830304, 2015). "All LRRK2-PD patients who complained of experiencing EDS reported that parkinsonism preceded the onset of this symptom." (PMID 26177462, 2015). "Mutations in several genes are reported to cause Parkinson’s disease (SNCA, LRRK2, VPS35, Parkin, PINK1, DJ-1)." (PMID 25759682, 2015). "The detergent data set also contained LRRK, the Drosophila ortholog of human LRRK2, the most common genetic determinant of Parkinson’s disease." (PMID 25453831, 2014). "The challenge is to clarify which specific functions of LRRK2 go awry in G2019S mutants, and how this eventually leads to parkinsonism." (PMID 25309331, 2014). "Mutations in LRRK2 are found at the PARK8 locus, and have been identified as a cause of a familial Parkinson's." (PMID 24115276, 2014). "Compared to sporadic Parkinson’s disease patients, LRRK2 patients had an earlier onset of motor symptoms and a more benign phenotype of motor and non-motor characteristics." (PMID 25391693, 2014). "Leucine-rich repeat kinase 2 (LRRK2) is known to play a role in the pathogenesis of various diseases including Parkinson disease, morbus Crohn, leprosy and cancer." (PMID 24465451, 2014). "As for the mechanism of LRRK2 involvement in the pathogenesis of Parkinson’s disease, studies have shown that LRRK2 regulates the degradation of defective Golgi, an organelle that contributes to synaptic vesicle formation." (PMID 24926233, 2014). "Mutations in the leucine-rich repeat kinase 2 gene (LRRK2) are the most common cause of inherited parkinsonism and account for a significant proportion of familial and sporadic Parkinson’s disease (PD) cases." (PMID 25330404, 2014).